IL6 (interleukin 6)
Diseases named in the same sentence as IL6 in open-access papers (continued):
Sharing a sentence is not in itself a finding about the gene and the disease.
hypertriglyceridemia (continued). "Second, hypertriglyceridemia induces the release of more inflammatory cytokines such as interleukin 6 and tumor necrosis factor alpha and reduces the release of anti-inflammatory cytokines such as interleukin 10, which may create a cellular environment conducive to neoplasia." (PMID 32967679, 2020). "IL-6, IL-1, and TNF-α are responsible for fever, whereas interferon-γ and TNF-α contribute to hypertriglyceridemia by inhibiting lipoprotein lipase and stimulating triglyceride synthesis." (PMID 35244052, 2022). "Clinical studies have indicated that patients with hypertriglyceridemia-induced AP often experience more severe abdominal pain, higher fever, and markedly increased levels of inflammatory markers such as C-reactive protein (CRP) and interleukin-6 (IL-6)." (PMID 40937420, 2025). "IL-6 and IL-1 β are involved in IR, which is mediated through the underexpression of insulin receptor substrate-1 (IRS-1), and also suppress the activity of lipoprotein lipase, resulting in hypertriglyceridemia." (PMID 39063997, 2024). "IL-6 production by adipose tissue could directly affect liver metabolism by inducing very low-density lipoprotein (VLDL) secretion and hypertriglyceridemia since the visceral adipose tissue is closely connected to the liver by the venous portal system." (PMID 29466985, 2018). "Hypertriglyceridemia may result from excess glucose consumption, and it has been reported that the rate of TG and fatty acid clearance is suppressed by cytokines, notably TNF-α, IL-6, and IL-1β, increasing this condition, as our data show." (PMID 39452936, 2024). "Furthermore, Matia-García and coworkers recently reported that young obese subjects with hypertriglyceridemia exhibit low-grade systemic inflammation characterized by increasing levels of C-reactive protein (CRP) and IL-6, accompanied by reduced IL-10 serum concentration." (PMID 29675435, 2018). "Investigating the involvement of IL-6 and IL-10 in the activation of STAT3 and NF-κB pathways and in the regulation of endocytosis via GSK3β inhibition or actin filament rearrangements could provide a deeper understanding of the increased BBB permeability seen in hypertriglyceridemia." (PMID 36882782, 2023).
intestinal inflammation (51 papers, 2014 to 2026). "Concerning the ENS, IL-6 increases neuronal excitability, and can participate in gastrointestinal dysfunction associated with intestinal inflammation or irritable bowel syndrome." (PMID 25497784, 2014). "Expert studies report elevated levels of IL-6 and IL-8 in gastroenteritis caused by rotavirus, which reinforces the idea that measurement of these interleukins could be a real tool in treating children with acute gastroenteritis." (PMID 39062898, 2024). "In particular, different studies have tried to establish a correlation between IL-6 and IL-8 levels, the acute phase of gastroenteritis, and the ability to distinguish its etiologies." (PMID 39062898, 2024). "The pro-inflammatory cytokine IL-6, and to a lesser degree IL-8, are involved in acute invasive gastroenteritis, such as shigellosis." (PMID 38091314, 2023). "Accordingly, G9P induced a significant upregulation of the IL-6 and IL-8 signaling pathways that have been previously shown to be involved in the pathogenesis of acute RVA-associated gastroenteritis." (PMID 37515094, 2023). "Proinflammatory cytokines, including TNF-α, IL-6, IL-1β, and IL-17, play an important role in drug-induced and spontaneous intestinal inflammation." (PMID 37660913, 2023). "Kaempferol dramatically reduced the extensive production of TNF-α and IL-6 in lipopolysaccharide-induced intestinal inflammation in rats." (PMID 36080365, 2022). "pointed out that LAB can inhibit p-IκBα, interfere with the NF-κB initiation, and represses the IL-1β and IL-6 levels in a mouse intestinal inflammation model." (PMID 35310848, 2022). "Taken together, these results indicate IL-6/STAT3 pathway plays an important role in the regulation of P2RY13-aggravated intestinal inflammation." (PMID 35982893, 2022). "At the same time, intestinal pathogens can invade intestinal epithelial cells, activate the intracellular signal transduction system, trigger the host immune response, stimulate the secretion of TNF-α, IL-6, and other inflammatory cytokines and mRNA expression, and induce intestinal inflammation." (PMID 39852407, 2025). "Interestingly, rectal administration of 0.3% NaOH solution induced intestinal inflammation, colon shortening, and upregulation of inflammatory cytokines IL-1β and IL-6." (PMID 39737965, 2024). "The intestine is one of the targets for Cd and its exposure may induce intestinal inflammation, and increase the levels of inflammatory factors such as IL-6 and TNF-α in the blood and intestine." (PMID 37565077, 2023). "Moreover, IL-6 can induce the proliferation of Th17 cells, which can secrete pro-inflammatory cytokines, such as IL-17 and TNF-α, to play pathogenic roles in intestinal inflammation." (PMID 33967768, 2021). "Furthermore, stool levels of both IL-6 and IL-8 were higher in gastroenteritis patients when compared with healthy controls, but due to technical difficulties linked to the enzyme-linked immunosorbent assay detection method, the biomarker characteristics of these fecal cytokines are debatable." (PMID 39062898, 2024). "Changes of IL-6 and TNF-α level may be closely associated with the attack, development and even recovery of diarrhea, and the moderate rise of TNF-α and IL-6 is conductive to the control over the body inflammatory reaction as well as the prevention from further development of gastroenteritis." (PMID 28798800, 2017). "Stress from separating piglets from their sows, along with dietary and environmental changes, can induce transient intestinal inflammation in piglets, characterized by increased pro-inflammatory cytokines TNF-α, IL-6, and IL-1β." (PMID 40336817, 2025). "Meanwhile, the levels of inflammatory cytokines (e.g., IL-6, IL-1β and TNF-α) were elevated, indicating the presence of intestinal inflammation." (PMID 40427600, 2025).
intestinal inflammation (continued). "The intestinal anti-inflammatory activity of esculetin (25 mg/Kg by oral route) in mice DSS-induced intestinal inflammation model was related to a reduction in MPO activity, counteraction of GSH depletion, and reduction in IL-6 production." (PMID 37111267, 2023). "Contrary to the anti-inflammatory cytokines, IL-1β, IL-6, and TNF-α, as pro-inflammatory cytokines which have been reported in the intestinal inflammation occurrence, were dose-dependently decreased by SSPs administration." (PMID 35359717, 2022). "Intestinal inflammation is related to higher TNF-α, IL-1β, and IL-6 levels." (PMID 37111225, 2023). "Although 4-methylesculetin was not reported as an inhibitor of the NF-κB signaling pathway, a reduction of pro-inflammatory cytokines production, such as IL-1β, IL-6, IL-17, and TNF-α was described in experimental models of intestinal inflammation at same doses." (PMID 37111267, 2023). "Intestinal inflammation is known to impair growth and development, as evidenced by elevated inflammatory markers such as C-reactive protein (CRP) and interleukin-6 (IL-6) be elevated in children with giardiasis and a link between chronic inflammation and stunting." (PMID 37816031, 2023). "We mimicked LPS-induced intestinal inflammation that could demonstrate the IAP-mediated decrease in the LPS-induced cytokine production of TNF-α and IL-6." (PMID 35958560, 2022). "NF-κB proteins are a major family of transcription factors, composed of subunits of the Rel family, p50 and p65, which play a key role in the regulation of proinflammatory gene transcription such as IL-1β, IL-6, TNF-α, Cox-2, iNOS, and adhesion molecules in the process of intestinal inflammation." (PMID 29853790, 2018). "Animal studies have suggested that lycopene could not only suppress the expression of pro-inflammatory factors like IL-1β, IL-6, IL-8 and TNF-α, but also stimulate the production of anti-inflammatory cytokines (such as TGF-β, IL-10), so as to reduce intestinal inflammation." (PMID 37608273, 2023). "The reason might be as follows: (a) MALT1 activated NF‐κB signaling pathway; meanwhile the activation of NF‐κB pathway was correlated with the secretion of various inflammatory cytokines (including IL‐1, IL‐6, TNF‐α, etc.)as well as the severity of intestinal inflammation." (PMID 34997981, 2022). "Another study highlighted the strong sensitivity and specificity performance of serum IL-6 in differentiating between viral and bacterial gastroenteritis, in contrast to IL-8, which presented similar increases in serum values of patients with gastroenteritis, regardless of etiology." (PMID 39062898, 2024). "In a 1-year study in Mongolia, IL-6 and TNF-alpha levels were studied in infants with benign seizures and acute gastroenteritis and compared with those without seizures and gastroenteritis." (PMID 39062898, 2024).
mucositis (51 papers, 2010 to 2026). Mucositis is inflammation and damage of the mucous membranes lining the mouth and other parts of the gastrointestinal (GI) tract. "As such, we measured secretion of the key inflammatory cytokine linked to intestinal tissue inflammation in mucositis, IL-6." (PMID 35867263, 2023). "Activation of NF-κB, which is the most studied pathway regarding mucositis development, drives the upregulation of genes that encode for several proinflammatory cytokines, e.g., interleukin-6 (IL-6) and tumor necrosis factor alpha (TNF-α)." (PMID 36451020, 2023). "Since one of the main mucositis causes is increasing inflammatory markers such as IL-2, IL-6 and etc, anti-inflammatory effects of atorvastatin is justifiable." (PMID 36420333, 2022). "Il6 production is a hallmark of many human chronic inflammatory states, including mucositis due to its pro-inflammatory properties." (PMID 33466324, 2021). "Three confounders were identified in the present study, as our data demonstrated that mucositis, weight loss, and smoking pack-years impacted levels of IL-6 and IL-10, whereas smoking pack-years had a strong influence on IL-18 serum levels, corroborating some earlier findings." (PMID 35682983, 2022). "IL-1β, TNF-α, and IL-6 were elevated during the third week of therapy, related to the development of worse mucositis in the oral cavity." (PMID 41220465, 2025). "Due to the few available studies, meta‐analyses comparing patients with mucositis to healthy controls and patients with peri‐implantitis to those with mucositis were conducted only for IL‐1β and IL‐6." (PMID 40101934, 2025). "Our results showed that both anthocyanidins reduced IL-6 levels in at least one intestinal region during mucositis induction, demonstrating their anti-inflammatory properties." (PMID 41226784, 2025). "All subgroups were homogeneous (I2 = 0%), except in the analysis of IL-6 in mucositis, which resulted in substantial heterogeneity (I2 = 65%)." (PMID 38686378, 2024). "Both IL-6 and IL-1β were observed to be significantly higher in peri-implant mucositis compared to healthy controls." (PMID 37384298, 2023). "Our results show that downregulation of AP-1 plays an important role in the development of mucositis by stimulating proinflammatory cytokines and chemokines such as IL-6." (PMID 36902486, 2023). "Considering the evaluation in the saliva, higher levels of IL-6 and IL-10 were found in individuals with mucositis in comparison to healthy individuals." (PMID 37355561, 2023). "In fact, expressions of TNF-α, IL-1β and IL-6 were also found to be increased in response to the 5-FU treatment, indicating that inflammatory cytokines play a key role in the pathogenesis of mucositis induced by chemotherapy and radiotherapy." (PMID 34310611, 2021). "Further evidences are mandatory to confirm the correlation between high-grade mucositis development and IL-6 or IL-1β levels in RT treated patients." (PMID 33028357, 2020). "This pilot study, due to its small sample size, cannot provide a definitive answer to the question of the relationship between levels of IL-6 and IL-8 and severity of mucositis during and after radiotherapy." (PMID 20184737, 2010). "These preliminary results, indicating a correlation between IL-6 and IL-8 serum levels and severity of mucositis and a need for a PEG tube installation, justify a large scale study." (PMID 20184737, 2010). "A positive correlation was found between IL-6 serum levels and severity of mucositis and dysphagia; specifically, high IL-6 levels at week 2 were correlated with a need for PEG tube installation." (PMID 20184737, 2010). "Periodontal pathogens can also enhance the proteolytic activity of microorganisms on the fibronectin on the oral soft tissue surface via adhesion receptors; this promotes inflammation through the release of pro-inflammatory cytokines IL-1 and IL-6 during radiotherapy-induced mucositis." (PMID 41228271, 2025).
mucositis (continued). "Significantly greater expression of IL‐6 was found in implants with mucositis and peri‐implantitis compared to healthy ones and in peri‐implantitis versus mucositis sites." (PMID 40101934, 2025). "All subgroups were homogeneous (I2 = 0%), except in the analysis of IL-6 in mucositis (I2 = 65%)." (PMID 38686378, 2024). "Initiation leads to messaging and signaling, and this then leads to the amplification stage of mucositis through a positive feedback loop with IL-1β, IL-6, and TNF-α being further transcribed, expediting and sustaining tissue damage of the mucosal cells lining the alimentary tract." (PMID 39080025, 2024). "Changes in IL-6 and IL-10 concentrations were significantly associated with mucositis, body weight change, and smoking pack-years, but not with the modality of treatment or tumor stage." (PMID 35682983, 2022). "TNF-α, IL-6, IL-1β, and cell apoptosis played a critical role in the development of mucositis." (PMID 33841399, 2021). "Moreover, evidence has indicated that the IL-6 level positively correlated with the severity of mucositis both in radiation-induced OM mice and in the head and neck of patients with cancer who underwent radiotherapy or radiochemotherapy." (PMID 33841399, 2021). "Therefore, it is believed that TNF-α, IL-1β and IL-6 are involved in mucositis and have been the targets of inhibition." (PMID 34310611, 2021). "In conclusion, the study demonstrated that AzP might regulate the MEK/ERK MAPK signaling pathway to attenuate MCP-1, TNF-α, and IL-6 production and provide opportunities for the development of new anti-inflammatory drugs targeting mucositis." (PMID 30634582, 2019). "Its role in potentiating inflammatory and immune responses by inducing various proinflammatory cytokines production such as TNF, IL-6 and IL-1β involved in the development of mucositis has been widely recognised with the use of animal models and in the clinical setting." (PMID 22973511, 2012). "Our study showed a correlation between high levels of IL-6 and severe mucositis." (PMID 20184737, 2010). "This study has shown for the first time, using the fractionated radiotherapy-induced mucositis rat model, that mRNA levels of pro-inflammatory cytokines, IL-1β, IL-6 and TNF, are significantly upregulated in the intestines following long term radiotherapy when compared to short term radiotherapy." (PMID 20233440, 2010). "Since TLR2 and IL‐6 are recognized to be crucial in the development of intestinal mucositis, future research should focus on testing whether wheat hydrolysates can be applied in clinical nutrition to attenuate mucositis." (PMID 30354027, 2018). "The hypertrophy/hyperplasia of the oral epithelium together with an increased expression of IL-6 and TNF-α resembles the early events of OM, which have previously been described in a contemporary model of mucositis development." (PMID 36451020, 2023). "Higher IL-6 and IL-10 levels in PICF of individuals with mucositis in comparison to healthy individuals were observed." (PMID 37355561, 2023). "Our study is also limited by its retrospective nature that hindered the uniform collection and incorporation of clinical and laboratory variables (e.g., GI symptoms, chills/rigors, mucositis, evidence of focal infection, CRP, PCT, IL-6, IL-8) into our models." (PMID 37113346, 2023). "NF-κB activation triggers the activation of multiple signaling pathways for the synthesis of different pro-inflammatory cytokines involved in various stages of mucositis, including TNF, IL-1β, and IL-6." (PMID 31936237, 2020). "During RT regimen, high-grade mucositis is more probably detectable either in patients characterized by a HPV/p16-negative status or in those producing an elevated salivary cytokine, IL-6 and IL-1β, concentration." (PMID 33028357, 2020).
mucositis (continued). "Many reports have indicated that patients undergoing chemotherapy would often experience the side effect of mucositis, with the pro-inflammatory cytokines IL-6 and TNF-α playing a key role in chemotherapy-induced mucositis." (PMID 30634582, 2019). "Pro-inflammatory cytokines regulated by NF-κB, such as IL-6, IL-1β and TNF-α, account for an important mechanistic component in the pathogenesis of mucositis." (PMID 28968968, 2017). "In the past decade, active research has been conducted to define the pathogenesis of mucositis and the role of proinflammatory cytokines TNF-α, IL-6, and IL-1β." (PMID 22973511, 2012). "NFκB is considered a key “driver” of chemotherapy-induced mucositis as its activation correlates with the production of TNF, IL-6 and IL-1β the hallmarks of mucositis inflammation." (PMID 22973511, 2012). "The first phase of mucositis during radio-chemotherapy was characterized by the production of inflammatory cytokines, such as IL-1, TNF-α and IL-6, that coordinate this process in the oral mucosa." (PMID 20184737, 2010). "Patients were evaluated for mucositis according to WHO common toxicity criteria, and blood samples were drawn for inflammatory (IL-1, IL-6, IL-8, TNF-α) and anti-inflammatory (IL-10) cytokine levels before and during treatment." (PMID 20184737, 2010). "Nuclear factor kappa B (NFκB), cyclooxygenase-2 (COX-2) as well as pro-inflammatory cytokines (in particular interleukin (IL)-1β (IL-6) and tumour necrosis factor (TNF)) have been suggested to play a key role in this 5 phase mucositis model." (PMID 20233440, 2010). "A relationship between high levels of IL-6 and a high grade of mucositis at week 4 was found (p = 0.081), but no such relationship between IL-1, TNF-α, IL-8 or IL-10 level and mucositis grade was shown." (PMID 20184737, 2010). "Of interest, Wardill and colleagues showed that TLR4 knockout BALB/c mice were less likely to develop severe mucositis and diarrhea after irinotecan treatment, possibly due to the absence of an IL-6 response." (PMID 39080025, 2024). "This transcription factor, which can also be directly activated by RT and/or CT, induces gene expression of proinflammatory cytokines such as interleukin-6 (IL-6), interleukin-1β (IL-1β), and tumor necrosis factor α (TNF-α), which are apparently increased in mucositis." (PMID 38473311, 2024). "In contrast, Dio efficaciously suppressed the expression of NF-κB downstream pro-inflammatory cytokines, including TNF-α, IL-6 and IL-1β in the ileums of CDDP-induced mucositis rats, and substantially promoted the production of the immunoregulatory mediators IL-10." (PMID 35457248, 2022). "They found an elevation in serum levels of cytokines IL-6, TNF-α and IL-1β which correlated with mucositis severity, and also showed that Amifostine did not reduce mucositis severity." (PMID 20184737, 2010).